EGF (epidermal growth factor)
Diseases named in the same sentence as EGF in open-access papers (continued):
Sharing a sentence is not in itself a finding about the gene and the disease.
ovarian carcinoma (continued). "We also demonstrate that PDE10A inhibition leads to decreased Wnt-induced β-catenin nuclear translocation, as well as decreased EGF-mediated activation of RAS/MAPK and AKT pathways in ovarian cancer cells." (PMID 36324187, 2022). "In our study, we explored the role of CA in the regulation of EMT in ovarian cancer, and we used the addition of EGF in the A2780 and SKOV3 cells to mimic the condition of the organism suffering from ovarian cancer." (PMID 35645793, 2022). "Elevated EGF levels also increased levels of VEGF and its receptor on ovarian cancer cells, further promoting ovarian cancer cell proliferation and migration." (PMID 35574025, 2022). "We examined the effects of hepatocyte growth factor (HGF), epidermal growth factor (EGF), and tumor necrosis factor alpha (TNFα), which are particularly relevant to the progression of ovarian cancer." (PMID 35676254, 2022). "COX-2 has been observed to be constitutively expressed in various ovarian cancer cell lines; introduction of PGE2 increases COX-2 expression, proliferation, invasion, reduction of apoptosis and secretion of EGF." (PMID 34503128, 2021). "The serum levels of other previously reported ascitic components, such as EGF, LPA, and uPA have also been reported to be elevated in ovarian cancer patients compared to controls." (PMID 34503128, 2021). "Within the ascites fluid and even plasma, notably in advanced-stage ovarian cancer patients, angiogenesis signaling proteins like VEGF and EGF are often present at elevated concentrations compared to patients with benign tumors or healthy controls." (PMID 34503128, 2021). "In ovarian cancer cells SKOV3 and OVCAR3, EGFR activation also increased SNAIL mRNA levels, which required EGF-induced H2O2 production and p38 MAPK activation." (PMID 35127732, 2021). "COX-2 derived PGE2 also promotes ovarian cancer cell invasion through an epidermal growth factor (EGF) signaling mechanism in which a positive feedback loop leads to increases in COX-2, PGE2 and EGF." (PMID 32982722, 2020). "Ovarian cancer cells typically display high expression of TRPC3, be they functional or suppressed, because of the Ca2+ increase stimulated by EGF (epidermal growth factor)." (PMID 32785177, 2020). "EGF induced MMP-9 and TIMP-1 expression in ovarian cancer cell lines has been shown to result in increased migration and robust EGF-induced invasion." (PMID 29393911, 2018). "Specifically, EGF induces the expression of GnRH-II by promoting CREB-dependent transcription, resulting in ovarian cancer invasion." (PMID 28439256, 2017). "We have shown that treatment with EGF up-regulates SPRY2 expression, and overexpression of SPRY2 attenuates EGF-induced E-cadherin down-regulation and cell invasion in human ovarian cancer cells." (PMID 27835572, 2016). "Previous studies have shown that AREG expression levels are significantly higher than EGF and TGF-α levels in ovarian cancer cells, tumor tissues and peritoneal and ascites fluid from patients with ovarian cancer." (PMID 27835572, 2016). "Our previous study has demonstrated that the constitutive phosphorylation of STAT3 is largely mediated through JAK1 in these ovarian cancer cells, suggesting a possibility of JAK1 as a main kinase responsible for activation of STAT3 by EGF blockade." (PMID 25928246, 2015). "Here, we show that epidermal growth factor (EGF) signaling upregulates LSD1 protein levels in SKOV3 and HO8910 ovarian cancer cells overexpressing both LSD1 and the EGF receptor." (PMID 26489763, 2015). "In this study, we show that EGF induces upregulation of LSD1, with a concomitant reduction of its substrate H3K4me2, which mediates the EGF-induced migration of SKOV3 and HO8910 ovarian cancer cells." (PMID 26489763, 2015). "This is the first study to examine the role of EGF, a mitogenic agonist that binds to EGFR, a tyrosine kinase receptor, on PAF production in ovarian cancer cells." (PMID 24721622, 2014).
ovarian carcinoma (continued). "In order to generate spheroid cells, ovarian cancer cell line OV2774 or primary EOC cells were enzymatically dissociated and inoculated on ultra-low attachment culture plates in serum-free medium with EGF, bFGF, and N2 supplement-A." (PMID 24409314, 2014). "We demonstrate that EGF increases the production of PAF in CAOV3 and SKOV3 ovarian cancer cell lines." (PMID 24721622, 2014). "In OVC Module 8, STAT5B-STAT3 gene pair is activated in ovarian cancer, interacts with each other, and is involved in many pathways including Jak-STAT signaling, RAS signaling, Chemokine signaling, EGF, IL10, PDGF, and TPO pathways." (PMID 23940583, 2013). "Controversially to our observations, a recent study showed that EGF decreased claudin-3 and -4 via MEK/ERK and/or PI3K/Akt signaling pathways in ovarian cancer cell lines." (PMID 24069372, 2013). "Although the contributions of EGF and EGFR signaling have been described in ovarian cancer, the majority of studies have been performed only on high-grade ovarian cancer cells." (PMID 22479527, 2012). "While initial studies suggested that EGF, due to the inability to detect transcripts in Northern blotting, might not play a significant role in ovarian cancer, subsequent studies indicated that exogenous EGF can also induce effects associated with transformation." (PMID 20037743, 2010). "The relationships between the observed activation of the JAK2/STAT3 pathway in ovarian specimens were correlated with EGF-induced phenotypic changes in OVCA 433 and SKOV3 ovarian carcinoma cell lines." (PMID 19088723, 2009). "In this study, we show that EGF regulates many of the key processes that lead to mesenchymal transition in epithelial ovarian cancer cells and that autocrine signalling through the IL6-R/JAK2/STAT3 pathway is associated with these events and may regulate the metastasis of ovarian carcinoma." (PMID 19088723, 2009). "The modulating effects of the epidermal growth factor (EGF) receptor-specific tyrosine kinase inhibitor ZM 252868 on cell growth and signalling have been evaluated in four ovarian carcinoma cell lines PE01, PE04, SKOV-3 and PE01CDDP." (PMID 10098742, 1999). "We have previously shown that epidermal growth factor (EGF) enhances the in vitro and in vivo sensitivity of human ovarian carcinoma 2008 cells to cisplatin." (PMID 7669570, 1995). "According to previous studies, EGF reduces the palmitoylation of CUB domain-containing protein 1 (CDCP1) and inhibits the palmitoylation-dependent degradation of CDCP1 to promote its expression on the cell surface of ovarian cancer cells." (PMID 40733034, 2025). "To assess the cytotoxicity of MSLN-CAR T cells against ovarian cancer stem cells (OCSCs), we derived sphere cultures from SKOV3 and OVCAR3 cells by culturing these in stem cell medium supplemented with EGF, FGF, and B27 (see “Materials and methods” for details)." (PMID 38637885, 2024). "Therefore, our experiment was based on EGF activation status of EGFR, and confirmed that activation of PKG I effectively inhibited the migration and invasion of ovarian cancer cells." (PMID 36653376, 2023). "EGF stimulation plays a role in matrix remodeling through the ERK and ILK/GSK-3 pathways in ovarian surface epithelial cells, and the combined targeting of endothelin and EGF receptors has been shown to increase antitumor activity in ovarian cancer." (PMID 38031074, 2023). "miR-503-5p suppression plays a critical role in CD97 expression (a member of the epidermal growth factor (EGF)—seven-transmembrane family, expressed in many cancers) and the related JAK2/STAT3 pathway for enhancing the metastasis of paclitaxel-resistant ovarian cancer cells." (PMID 38139300, 2023). "Activated PKG I also inhibited ovarian cancer proliferation, invasion, and metastasis in the absence of EGFR activation, but the effect was less significant than that of EGF-stimulated therapy." (PMID 36653376, 2023).
ovarian carcinoma (continued). "Using breast, pancreatic, and ovarian cancer cells, transforming growth factor beta-1 (TGFB1) or epidermal growth factor (EGF) treatment or SNAI1 overexpression increased stemness and reduced let-7 expression, while SNAI1 knockdown reduced stemness and increased let-7 expression." (PMID 33806868, 2021). "In addition, the under-expression of LCN2 was correlated inversely with the severity of ovarian cancer, and in vitro study showed marked enhanced EMT and cellular spread after epidermal growth factor induced inhibition of LCN2 expression." (PMID 34062746, 2021). "EGF induces the production of both COX-2 and PGE2 via the activation of the PI3K/Akt signaling pathway, resulting in an invasion of SKOV3 and OVCAR5 cells (two human ovarian cancer cell lines)." (PMID 32363546, 2020). "CD97 is a member of the epidermal growth factor (EGF)-seven transmembrane family that signals through Janus-activated kinase 2(JAK2), a signal transducer and activator of transcription 3 (STAT3), to induce paclitaxel resistance in ovarian carcinoma." (PMID 32850313, 2020). "Our previous report supports this statement because we clearly demonstrated that KP could potently suppress EGF-induced ERK1/2 and PI3K/Akt phosphorylation in HeLa cervical cancer cells and SKOV-3 ovarian cancer cells." (PMID 31470515, 2019). "Previously, we demonstrated that EGF or TNF could induce the expression of proinflammatory chemokines such as CXCL1, 2, 3 and 8 in ovarian cancer cells via NF-κB, Akt and Erk signaling pathways." (PMID 30034618, 2018). "Furthermore, LH appears to activate the PTP pathway via Ga(i) and counteracts mitogenic signal transduction induced by EGF, suggesting that the interaction of LHR and EGFR is essential for determining the fate of ovarian cancer cells." (PMID 28439256, 2017). "It is important to highlight that EGF and NGF are overexpressed in ovarian cancer." (PMID 26091707, 2016). "In this study, we demonstrate that EGF stimulates the phosphorylation of PLCβ, which can be blocked by the EGFR inhibitor AG1478, suggesting that the crosstalk occurs bidirectionally between EGFR and PAFR in ovarian cancer cell lines." (PMID 24721622, 2014). "The results concerning the role of cPLA2 in EGF-induced PAF production, along with the convergence of signaling molecules on cPLA2, suggest that cPLA2 may be a potential therapeutic target in ovarian cancer." (PMID 24721622, 2014). "Whether EGF could affect the expression of cPLA2 and whether cPLA2 could affect the production of PAF requires further research in ovarian cancer cells." (PMID 24721622, 2014). "Extracellular signals that induce VEGF-A through this proximal region include, among others, growth factors such as EGF, insulin and PDGF in fibroblasts, prostaglandin E2 in human muscle cells, M-CSF in monocytes and lysophosphatidic acid (LPA) in ovarian cancer cells." (PMID 23506169, 2013). "Using RPPA, we analyzed the expression level of 153 proteins and/or phosphorylation sites in Huaier-treated or untreated ovarian cancer cell lines with or without EGF stimulation." (PMID 23667667, 2013). "These combined data suggested that by MMP9 inhibition might abolish EGF-HGF induced cellular invasiveness and, therefore, it could be a potential target therapy for ovarian cancer." (PMID 23320251, 2012). "The ARID3B Sh splice form was verified using DOV13 and OVCA 429 ovarian cancer cells treated with or without EGF for 24 h." (PMID 22860069, 2012). "In addition, it seemed that EGF and HGF cooperate to promote invasiveness in ovarian cancer cell lines through increase secretion of MMP9 and the inhibition of MMP9 abolished EGF and HGF induced cellular invasion." (PMID 23320251, 2012).
ovarian carcinoma (continued). "It has been shown that EGF can induce EMT in ovarian surface epithelium (OSE) and ovarian cancer cells, suggesting that EGF may be involved in ovarian cancer pathogenesis and metastasis." (PMID 22479527, 2012). "In contrast, significant inhibition in cell motility was observed within 14 h in EGF-treated cells in the presence of AG490 (100 μM), indicating that JAK2/STAT3 pathway may be involved in the EGF-induced motility of ovarian cancer cells." (PMID 19088723, 2009). "To determine if mRNA increase in IL-6R expression in response to EGF treatment has any affect on the production of IL-6 in ovarian cancer cell lines, we used IL-6 sandwich ELISA to quantify the amount of IL-6 secreted by OVCA 433 and SKOV3 cell lines in response to EGF." (PMID 19088723, 2009). "However, one study has reported that 3-O-sulfation by HS3ST2 traps growth factors including EGF and inhibits signal activation in ovarian cancer, although the interaction has not been shown in direct binding experiments." (PMID 37463954, 2023). "However, the PKG I agonist had no significant anti-ovarian cancer therapeutic effects in the absence of EGF, consisting with previous reports." (PMID 36653376, 2023). "Curcumin was found to inhibit EGF-induced upregulation of AQP3 and migration in human ovarian cancer cells, via inhibition of AKT/ERK and PI3K pathways; however, curcumin affects a number of biochemical pathways and might not be suited when AQP-specific modulation is required." (PMID 29922644, 2018). "Since epidermal growth factor receptor (EGFR), which is highly expressed in ovarian cancer cells, is a very important factor for tumor growth, we therefore stimulated SKOV3 cells with EGF and performed MTT assay to evaluate whether KP still be able to suppress cell viability." (PMID 29891015, 2018). "The results show that EGF could not promote the growth of ovarian cancer cells in which PTTG expression had been silenced compared with control cells." (PMID 26516926, 2015). "Furthermore, a recent study demonstrated that EMT is required for EGF-induced large gastric cancer (LGC) and ovarian cancer cell migration and invasion, and that EGF-induced EMT involves activation of the ERK1/2 and PI3K/AKT pathways with subsequent induction of Snail, Slug, and ZEB1 expression." (PMID 24945379, 2014). "However, an increase of EGF was found in pancreatic and papillary thyroid carcinoma, and no alterations were found in ovarian cancer, suggesting that its biological function is tissue-dependent." (PMID 17453000, 2007). "Furthermore, since Tamoxifen and ICI 182780, antagonists to nuclear ERs, and G-1, a specific GPER agonist, mimicked this effect of estradiol, we concluded that estrogen modulation of EGF induced migration in ovarian cancer cells was mediated by GPER, not by ERα." (PMID 22424333, 2012). "The current study revealed the suppression of higher EGF levels, as well as EGFR levels after PPE treatment to ovarian cancer cells OVCAR-3, with no impact on non-cancerous HGL5 cells." (PMID 38027211, 2023). "We transduced human ovarian cancer cells, OVCA 429, with lentiviral particles expressing GFP, ARID3B Fl or ARID3B Sh, and treated cells with or without 20 nM EGF." (PMID 22860069, 2012). "Interestingly, cisplatin treatment increases AREG promoter activity but not EGF or TGF-α promoter activity, suggesting a possible role of AREG in regulating chemoresistance in ovarian cancer." (PMID 27835572, 2016).
pancreatic cancer (176 papers, 1990 to 2025). "In this study, we found a significant association between pancreatic cancer driver genes, EGF, EPHB3, and POTEF, and original.glrlm.RunVariance." (PMID 38811597, 2024). "The group of Michael Karin found an increase in several EGFR ligands including EGF after mutationally activated NRF2 in a mouse model of hepatomegaly as well as in human pancreatic cancer cells with ATG7 deletion." (PMID 33916908, 2021). "Under high-glucose conditions (diabetes), which is a risk factor for pancreatic cancer, curcumin suppressed EGF levels and activation of EGFR and ERK, resulting in reduced invasive ability and inhibition of metastatic-related factors." (PMID 34867402, 2021). "For instance, in pancreatic cancers, epidermal growth factor (EGF) and/or human epidermal receptor-2 (HER-2) mutations are critically responsible for cancer cell proliferation." (PMID 33305295, 2020). "Recently, Korc and coworkers reported that downregulating Tat-interacting protein 30 (TIP30) and upregulating EGFR by miR-10b microRNA caused EGF-mediated invasion in pancreatic cancer." (PMID 27240340, 2016). "Our data provide evidence that the stress-induced increase in pancreatic tumor growth was due to stimulation of tumor cell β-ARs and the associated stimulation of the AA pathway, EGF cascade, Src and AKT pathways, as well as VEGF interactions." (PMID 22916251, 2012). "Concomitant expression of epidermal growth factor receptor (EGFR) with its ligand, such as EGF, transforming growth factor α (TGFα) or amphiregulin has been associated with decreased patient survival in pancreatic cancer." (PMID 16822304, 2006). "Amphoteric regulatory protein (AREG), a member of the epidermal growth factor (EGF) family, is upregulated in pancreatic cancer." (PMID 40448344, 2025). "In pancreatic cancer cells (BxPC-3), inhibition of the epidermal growth factor (EGF)/extracellular signal-regulated kinase (ERK) and EGF/AKT pathways has also been observed, confirming its ability to affect growth receptors and tumour proliferation." (PMID 41226384, 2025). "For example, constructing pancreatic cancer organoids typically requires the addition of growth factors like epidermal growth factor (EGF) and fibroblast growth factor (FGF) to promote organoid growth and differentiation." (PMID 41488666, 2025). "In pancreatic cancer, EGF signaling triggered the EMT via integrin/EGFR/MAPK signaling, which induces decreases in E-cadherin and ZO-1." (PMID 38263290, 2024). "MSI2 also facilitates EMT in pancreatic cancer induced by EGF through the ZEB1-ERK/MAPK signaling pathway." (PMID 39097735, 2024). "MSI2 also promotes EMT induced by EGF in pancreatic cancer through the ZEB1-ERK/MAPK signaling pathway." (PMID 39097735, 2024). "Having observed that treating PANC1 cells with HMT increased the SAH/SAM ratio, we analyzed the localization of MRAS in EGF-stimulated pancreatic cancer cells." (PMID 37996408, 2023). "Previous studies have reported that potato carboxypeptidase inhibitors can inhibit the proliferation of pancreatic cancer by acting as a competitive inhibitor of epidermal growth factor (EGF) and by binding to EGFR." (PMID 36674593, 2023). "It promotes EGF-induced pancreatic cancer cell proliferation by targeting Spry2, and the mechanistic revealed that miR-21 targeted MAPK/ERK and PI3K/AKT signaling pathways to modulate cell proliferation." (PMID 36688087, 2023). "Because HepG2 cells express low levels of EGFR26, we tested EGF-TAMRA binding to a human pancreatic cancer cell line, PANC-1, which expresses high levels of EGFR." (PMID 37061516, 2023). "Among the BiXAbTM that most strongly inhibited the phosphoproteome in pancreatic cancer cells stimulated with the EGF+NRG1 ligand mix, anti-EGFR/HER3 BiXAbTM, including 3Patri-1Cetu-Fc and 3Patri-1Matu-Fc, were consistently more effective." (PMID 37153618, 2023).